BDNF (brain derived neurotrophic factor)
Diseases named in the same sentence as BDNF in open-access papers (continued):
Sharing a sentence is not in itself a finding about the gene and the disease.
depression (continued). "This factor repressed brain-derived neurotrophic factor (BDNF) expression and caused depression-like behaviors in male mice." (PMID 36578534, 2022). "As such, exercise contributes to decreasing in the level of cortisol and increasing the brain neurotransmitters (i.e., BDNF, serotonin, dopamine), these positive hormones then play a key role in reducing the depression and suicide-related outcomes." (PMID 35886707, 2022). "In this study, 5300 published documents were collected using bibliometrics to clarify the current status and future trends of research on the role of BDNF in depression." (PMID 36291673, 2022). "In summary, fRG and its constituents mitigated anxiety/depression and colitis by regulating NF-κB-mediated BDNF expression and gut dysbiosis in rodents." (PMID 36499295, 2022). "It significantly mitigated depression-like behaviors in chronic, unpredictable mild-stress rats, restoring brain-derived neurotrophic factor (BDNF) levels and neural growth in the hippocampus." (PMID 36014776, 2022). "Low circulating BDNF levels were suggested as a biomarker for major depression, and increase in their levels is indicative of successful treatment of mood disorders." (PMID 36160856, 2022). "Another study showed that Bifidobacterium E41 and M2CF22M7 suppressed depression-like behaviors via improving the microbial dysbiosis and enhancing expression levels of serotonin and BDNF." (PMID 36358502, 2022). "As synaptic plasticity is impaired, or otherwise maladaptive, in various neuropsychiatric disorders including depression, its facilitation by BDNF represents an important potential therapeutic mechanism." (PMID 35955546, 2022). "Stressful life events have been demonstrated to be related to low brain-derived neurotrophic factor levels and higher vulnerability to depression in a murine model and in human epigenetic research." (PMID 35564525, 2022). "Extracellular vesicles derived from Lactobacillus plantarum (L-EV) have been shown to reverse the reduced BDNF expression and block stress-induced depression-like behaviors." (PMID 36499295, 2022). "Like ketamine, esmethadone blocks tonic NMDAR-mediated Ca2+ influx and induces brain-derived neurotrophic factor (BDNF)-dependent neural plasticity in animal models of depression, reversing depressive-like behavior." (PMID 36293063, 2022). "Research has shown that the level of BDNF in the hippocampus and prefrontal cortex is significantly reduced in patients with depression." (PMID 35496273, 2022). "This study would have been more informative if we had measured other known biomarkers of depression including brain-derived-neurotrophic factor, which is frequently reduced in clinical depression." (PMID 35330475, 2022). "In line with this, lipopolysaccharide-induced inflammation decreased BDNF in the hypothalamus and resulted in depression-like behaviors in rat models." (PMID 36578534, 2022). "Sirtuin type 1 (SIRT1) has been proved to be involved in many pathological mechanisms of depression, including glial activation, neurogenesis, circadian rhythm, inflammatory reaction and BDNF signaling." (PMID 35664490, 2022). "Using animal models of depression, antidepressant effects have been produced after BDNF injection into the hippocampus (Castrén and Rantamäki, 2010)." (PMID 35967846, 2022). "It has been demonstrated in animal models that electroconvulsive seizures (ECS, a recognized ECT analog in animal experiments) can elevate BDNF levels in the hippocampus while improving depression-like behavior." (PMID 36457756, 2022). "Another melatonin receptor agonist, ramelteon, improves depression and anxiety symptoms by increasing BDNF levels and targeting clock genes (e.g., Per1 and Per2)." (PMID 36699021, 2022). "Among these genes, brain derived neurotrophic factor (BDNF) has been recently found in both obesity and depression." (PMID 35911513, 2022).
depression (continued). "The main objective of this study was to compare the biological differences between reactive depression and endogenous depression in terms of immune-inflammation, BDNF, DA, and HPA axis-related indicators." (PMID 35295780, 2022). "Direct injection of ANA-12 to nucleus accumbens replicates the antidepressants effects, which is consistent with earlier studies showing that BDNF injection into this region produces a depression-like phenotype." (PMID 36407765, 2022). "According to increasing evidence, the interaction of BDNF-TrkB and dopamine (DA) signaling in midbrain circuits plays a major role in the pathophysiology of depression." (PMID 35757201, 2022). "In depression models, magnolol from Magnolia officinalis bark altered brain BDNF level as well as serotonergic, noradrenergic and dopaminergic neurotransmission." (PMID 36419621, 2022). "Another study showed that specific-pathogen-free mice treated with oral antimicrobials showed transiently perturbed gut microbiota, leading to increased hippocampal BDNF concentrations and the subsequent prevention of depression." (PMID 36499295, 2022). "There is evidence that increasing the expression of BDNF in hippocampal astrocytes can treat depression and anxiety and stimulate hippocampal neurogenesis." (PMID 36408279, 2022). "There was also a study showing that acute high-intensity intermittent exercise increased serum BDNF concentration and attenuated the emotional states of tension, depression, and anger." (PMID 36233452, 2022). "The content of BDNF in blood plasma decreases in people suffering from depression and returns to normal levels after an antidepressant treatment." (PMID 35337082, 2022). "Nevertheless, there is mounting evidence that BDNF signaling can integrate diverse environmental and therapeutic cascades and holds promise as a pharmacological jack of all trades in the depression field." (PMID 36430921, 2022). "Emerging evidence has also shown that the expression of BDNF diminishes in animal models of depression and depressed patients." (PMID 36668838, 2022). "Further, the severity of mania and depression in BD patients seems to inversely correlate with BDNF levels." (PMID 35835742, 2022). "Taken together, our results indicate that PRE upregulates BDNF levels against CORT-induced depression-like phenotypes by regulating the HPA axis through normalizing GR function via inhibition of Ser211-mediated GR phosphorylation." (PMID 35684372, 2022). "Collectively, this study provides a comprehensive summary and analysis on the role of BDNF in depression and its treatment and offers meaningful values for beginners on this topic." (PMID 36291673, 2022). "Mainly expressed in the hippocampus, cortex, amygdala, and striatum and also in the hypothalamus, BDNF is a protein known to be involved in brain plasticity and depression." (PMID 35721194, 2022). "The level of BDNF decreased in both the brain of patients with depression and in animal models of depression." (PMID 35140618, 2022). "In the chronic unpredicted mild stress-induced depression mouse model, DHM’s action against depression is associated with the upregulation of brain-derived neurotrophic factor (BDNF) and inhibition of inflammation in the hippocampus." (PMID 36496991, 2022). "Clinical studies have demonstrated that BDNF is an important factor in the pathogenesis of depression." (PMID 35684372, 2022). "Patients with COPD with psychological symptoms such as anxiety and depression show decreased serum BDNF levels." (PMID 36299904, 2022). "It has been found that a decrease in BDNF levels is common in psoriasis and depression, which is a possible factor linking psoriasis with depression." (PMID 35054853, 2022). "Both acute exercise and long-term aerobic exercise are powerful forms to improve the brain-derived neurotrophic factor, a biomarker of depression in serum." (PMID 36159294, 2022).
depression (continued). "Decreased serum or plasma levels or reduced BDNF expression in the hippocampus were found in major depression and stress." (PMID 36498925, 2022). "Our previously published report in the depression animal models, HTP-GTE modulated the BDNF-TrkB pathway which was associated with improving cognitive impairments caused by post-menopausal depression." (PMID 35198737, 2022). "Porphyromonas gingivalis (Pg) downregulates BDNF maturation, leading to depression-like behavior in mice." (PMID 36499295, 2022). "According to sensitivity analysis, no single study had a substantial impact on the notable difference in blood BDNF levels between depression patients and healthy controls." (PMID 35510613, 2022). "In summary, some specific emotional and physiological parameters during experimental ayahuasca session were revealed as critical moderators of the improvement of major depression biomarkers, mainly BDNF and SC two days after ayahuasca intake." (PMID 36545037, 2022). "Studies have suggested that BDNF is key to learning, memory, and mood regulation and is involved in many neuropsychiatric disorders, including depression." (PMID 35572711, 2022). "It proved that AFR has therapeutic effects on depression by verifying the BDNF-MEK signalling pathway and NLRP3/caspase-1 inflammatory signalling pathway in vitro and in vivo." (PMID 35938494, 2022). "It has been reported that low serum BDNF levels in patients with depression, were significantly increased by antidepressant treatment." (PMID 35684372, 2022). "BDNF, the most important neurotropin in the brain, is a candidate target for the treatment of depression." (PMID 36552159, 2022). "Bundles of previous clinical and animal studies have revealed that chronic stress induces a reduction in the level of depression biomarkers such as BDNF." (PMID 36686688, 2022). "This difference between NGF and BDNF mimetics is probably related to the differences in the TrkA and TrkB expression in the brain structures involved in the depression pathogenesis." (PMID 35337082, 2022). "55-57 Investigations that have evaluated BDNF in other psychiatric disorders, such as schizophrenia, major depressive disorder, bipolar disorder, and suicide behavior, also showed a similar pattern to that detected in our analyses." (PMID 34060728, 2022). "Several studies have shown that BDNF levels are decreased in mental disorders such as depression, schizophrenia, anxiety disorders, and cognitive impairment, to name a few." (PMID 35836661, 2022). "The authors showed that SD induced cognitive impairment, increase of anxiety, depression, cortisol levels, and brain-derived neurotrophic factor (BDNF) levels, whereas decreased frontal blood activation." (PMID 36225892, 2022). "Brain-derived neurotrophic factor plays an important role in neuroplasticity and the pathophysiology of depression." (PMID 36498934, 2022). "As such, lower BDNF levels raises the vulnerability to depression, with which eating disorder frequently co-exist as they share common biological mechanisms." (PMID 35850718, 2022). "The neurotrophic theory of depression initially assumed that environmental stress decreases BDNF levels in the brain, which results in decreased neuroplasticity and morphological changes, such as hippocampal shrinkage." (PMID 35448545, 2022). "This also applies for the complex BDNF-serotonin interactions in the understanding and treatment of various psychopathologies, especially in mood disorders such as anxiety and depression." (PMID 35955546, 2022). "Compelling evidence demonstrated a crucial role for BDNF signalling in different central nervous system disorders, including major depression, with reduced brain levels in depressive patients’ brains and peripheral tissues." (PMID 36430520, 2022). "Our sub‐group analysis showed that a history of depression and alcohol consumption had an effect on the level of BDNF." (PMID 35510613, 2022).
depression (continued). "The correlation analysis revealed that the level of BDNF at baseline correlated positively with the HDRS depression symptom score (r = 0.415; p = 0.0228)." (PMID 35448545, 2022). "On the other hand, the local infusion of BDNF in the hippocampus (HC) mimics the behavioral effects of antidepressants but elicits depression-like behaviors if infused in the VTA." (PMID 36499323, 2022). "Another study showed that, in human cerebrospinal fluid, levels of pro-peptide BDNF (pro-domain of BDNF, pBDNF) were significantly lower in patients with major depressive disorder than in controls." (PMID 36158555, 2022). "Our results indicate that the basal levels of BDNF/trkB-LI are lower in the PFC of depression-prone RLA rats vs. their RHA counterparts." (PMID 36499323, 2022). "Additional studies were done in a post-stroke rat model of depression, as depression is the most common neuropsychiatric consequence of stroke, and studies have shown that decreased serum BDNF in post-stroke patients can be an early indicator of depression." (PMID 36429060, 2022). "In pregnant or postpartum women suffering from depression, the neurotrophin brain-derived neurotrophic factor (BDNF) has consistently been shown reduced compared to healthy controls." (PMID 34989854, 2022). "It has been reported that knocking out ERα induces depression in mice and reduces hippocampal BDNF and the phosphorylation of its downstream targets TrkB, AKT, and extracellular regulatory protein kinase 1/2 (ERK1/2)." (PMID 36408279, 2022). "We conducted this meta‐analysis to expand our current knowledge in this issue by performing a comprehensive analysis of all the currently available data related to BDNF and depression." (PMID 35510613, 2022). "In a lupus-prone MRL/lpr old mice model of depression, fish oil and conjugated linoleic acid all increased the expression levels of BDNF and synaptic protein in the brain." (PMID 36358502, 2022). "Considering that BDNF expression is reduced in the pathophysiology of depression, the study examined the effects of R-ketamine and S-ketamine treatment on astrocytes under normal conditions and tunicamycin-induced ER stress." (PMID 35456680, 2022). "In a previous study, we found evidence for a positive correlation between BDNF gene methylation level and BDNF protein levels at CpG sites 1 and 6 in a sample consisting of bipolar and unipolar depression patients and healthy controls." (PMID 34989854, 2022). "Ketamine has similar effects, upregulating BDNF and improving depressive symptoms (decreasing Hamilton Depression Rating Scale score)." (PMID 36294343, 2022). "Our meta‐analysis aims to evaluate and update the current status of peripheral BDNF with depression." (PMID 35510613, 2022). "Recent animal studies have proven that chronic unpredictable mild stress can significantly reduce the expression of BDNF in the pathogenesis of depression." (PMID 35848938, 2022). "The expression levels of the serotonin transporter (5-HTT) and brain-derived neurotrophic factor (BDNF) in the hippocampus of the rats with depression were markedly increased by GMDZ." (PMID 35161241, 2022). "Human interventional trials investigating the effects of probiotics on depression and serum BDNF are already arising." (PMID 36555576, 2022). "A meta-analysis demonstrated substantial reductions in peripheral BDNF levels in manic and depressive episodes of BD." (PMID 35163764, 2022). "Based on previous studies, BDNF levels in the hippocampus and prefrontal cortex are reduced in cases of depression." (PMID 36014336, 2022). "In CMS mouse model, BDNF signaling pathway in the hippocampus was boosted due to Rg2 administration, which inhibited the depression-like effects induced by CMS, and knocking out TrkB can entirely block the antidepressant effect of Rg2 in mice." (PMID 35795547, 2022).
depression (continued). "The increase in endogenous BDNF, in turn, attenuates the symptoms of depression by reversing neuronal atrophy and promoting cell proliferation in the hippocampus and prefrontal cortex." (PMID 36506414, 2022). "The possible common biological mediators between depression and lung tumorigenesis are abnormalities in GC secretion, inflammatory response and BDNF function." (PMID 36417428, 2022). "In a rat model of male hypogonadism, resveratrol alleviated depression-like behaviors via increasing hippocampal and prefrontal cortical levels of BDNF and neurotrophin-3." (PMID 36358502, 2022). "BDNF is a key member of the neurotrophic family and plays an important role in stress-related depression." (PMID 35888708, 2022). "The BDNF-TrkB signaling pathway is considered a drug target for a wide range of neurological diseases and depression." (PMID 35890231, 2022). "Currently, there is a large number of studies on the role of BDNF in the pathogenesis and therapeutic mechanism of depression." (PMID 36291673, 2022). "Understanding the role of BDNF signaling in the hypothalamus will lead to valuable insights for sex- and stress-dependent neurobiological underpinnings of depression pathology." (PMID 36466807, 2022). "This compound mimics the processes taking place in the development of depression, i.e., by inhibiting protein glycosylation, resulting in accumulation of misfolded proteins in astrocytes and decreasing the release of BDNF in astrocytes." (PMID 35456680, 2022). "Curcumin potentially improves depression-like behavior by modulating stress hormones, hippocampal neurotransmitters, and BDNF levels in rats." (PMID 36499295, 2022). "In HD patients with self-reported depression (n = 51), the biochemical parameters showed BDNF was negatively correlated with inflammatory marker ferritin (rs = − 0.44; p = 0.008)." (PMID 35292710, 2022). "On the other hand, the peripheral blood concentration of brain derived neurotrophic factor (BDNF) was lower among the patients with comorbid diabetes and depression." (PMID 35253006, 2022). "BDNF depletion can lead to psychiatric disorders, such as depression, anxiety, attention-deficit/hyperactivity disorder, and drug addiction." (PMID 36611538, 2022). "Multiple lines of evidence suggest that BDNF and its receptor TrkB play a crucial role in depression and in the mechanisms of antidepressants." (PMID 36550125, 2022). "The myokine brain‐derived neurotrophic factor (BDNF) is known to be altered in depression and levels are significantly altered in germ‐free animals who have no microbiota." (PMID 35819136, 2022). "Meanwhile, a positive relationship between SIRT1 and BDNF expression in mPFC and SIRT1 inhibitor limited the role of S-ketamine in reducing the depression-like behavior and increasing the BDNF level." (PMID 35664490, 2022). "In the present study, p-CREB/CREB ratio and BDNF expression level decreased in hippocampus of mice with CUMS-induced depression and echinacoside up-regulated BDNF level and p-CREB/CREB ratio." (PMID 36686689, 2022). "Brain-derived neurotrophic factor (BDNF) and TrkB play crucial roles in cognition, memory, and depression, driven at least in part by downstream effectors, including VGF (non-acronymic)." (PMID 35909451, 2022). "One study reported that NBP acts as a therapeutic agent for depression-like behaviors through the modulation of the serotonergic system and BDNF–ERK–mTOR signaling." (PMID 36499295, 2022). "Severity of depression, global cognition and the serum brain‐derived neurotrophic factor (BDNF) level were evaluated at baseline, 3‐, 6‐ and 12‐week follow‐ups." (PMID 35912517, 2022). "To confirm that BDNF and its major ligand-specific receptor TrkB mediates induces C/EBPβ-induced depression, we treated WT and Thy1-C/EBPβ Tg male mice with 7,8-DHF during the last 4 weeks of a 12-week HFD course a." (PMID 36578534, 2022).